PLXNB2 (plexin B2)
Diseases named in the same sentence as PLXNB2 in open-access papers (continued):
Sharing a sentence is not in itself a finding about the gene and the disease.
cancer (20 papers, 2016 to 2025). A tumor composed of atypical neoplastic, often pleomorphic cells that invade other tissues. "In a previous study, we demonstrated that higher PlxnB2 signaling was associated with increased MCF7 cancer cell migration." (PMID 36722641, 2023). "The importance of G842‐mutated PlxnB2 in cancer invasion was further assessed in the framework of CUP cells carrying an endogenous wild‐type gene." (PMID 36722641, 2023). "Altogether, these data suggest that AS43 cancer cells are specifically dependent on G842C‐mutated PlxnB2 for stem properties and proliferation." (PMID 36722641, 2023). "In sum, we found that a novel activating mutation of the axon guidance gene PLXNB2 sustains proliferative autonomy and confers invasive properties to stem cells isolated from cancers of unknown primary, in EGFR‐dependent manner." (PMID 36722641, 2023). "Loss of plexin-B1/plexin-B2 could represent a mechanistic basis for the loss of contact inhibition, a hallmark of cancer." (PMID 37627074, 2023). "Taken together, these data strongly suggest that loss of Plexin-B1/Plexin-B2 could represent a mechanistic basis for the loss of contact inhibition, a hallmark of cancer that has remained poorly understood on a molecular level." (PMID 33637728, 2021). "Notably, previous studies have implicated this axon guidance receptor in the regulation of cancer cell proliferation, invasiveness, and metastatic spreading; however, nothing was known about PLXNB2 mutations in cancer, or in other settings." (PMID 36722641, 2023). "In this work, we also showed that angiogenin and its two recently identified receptors, EGFR and PLXNB2,45,58 were upregulated at the protein level by ccRCC cancer cells as compared to their cell type of origin ex vivo." (PMID 38025776, 2023). "Consistent with previous findings, PlxnB2‐WT overexpression promoted basal cancer cell migration to some extent; however, here we found that this effect was far more pronounced in the presence of G842C‐mutated receptor." (PMID 36722641, 2023). "Overexpression of Plexin-B2 and SEMA4C has been implicated in the poor prognosis in the cancers of bone, breast, and brain." (PMID 35570846, 2022). "The role of circPLXNB2 derived from the PLXNB2 gene has rarely been studied in cancer, let alone in AML." (PMID 33757550, 2021). "The strongly reduced expression levels of Plexin-B1 and Plexin-B2 correlated with an impaired ability of the primary human cancer cells to exclude YAP from the nucleus at high cell densities." (PMID 33637728, 2021). "Intriguingly, we found that mechanosensation through Plexin-B1/Plexin-B2 regains biological relevance in the adult murine epidermis for the suppression of cancer cell proliferation." (PMID 33637728, 2021). "The dichotomous functions of ANG and PLXNB2 in HSPCs and MyePros prompted us to examine their function in prostate CSCs and in differentiated cancer cells, based on the rational that CSCs and HSPCs are regulated by similar mechanisms." (PMID 31942000, 2020). "The PLXNB subgroup were associated with both survival advantage and disadvantage of a number of cancer types, but PLXNB1 and PLXNB2 were more associated with better survival, while PLXNB3 was more associated with worse survival." (PMID 32640719, 2020). "From our top 10 specific TFs, only 3 are differently expressed in this cancer type (PLXNB2, NRG1, SAP30BP)." (PMID 33057419, 2020). "Among them, SEMA3F, SEMA4C, PLXNB1 and PLXNB2, involved in cancer progression and in immune system suppression, were highly expressed." (PMID 26784191, 2016). "In cancer, this could mean that PLXNB2-semaphorin signaling may contribute to forming a more adhesive and supportive environment for both cancer cells and immune cells, facilitating metastasis." (PMID 40818975, 2025). "In cancer zone B, the SEMA4 pathway relied on Sema4a-Plxnb2, Sema4d-Cd72, and Sema4d-Plxnb2 interactions, with Sema4a/d-Plxnb2 showing particularly strong communication between cancer_macro 1 cells." (PMID 40723284, 2025).
cancer (continued). "In the TME, ANG is expressed by cancer cells, EGFR is expressed mostly by cancer cells and to a lesser extent by fibroblasts, and PLXNB2 is expressed mainly by dendritic cells, macrophages, and cancer cells." (PMID 38025776, 2023). "Notably, a recent report indicated that plexin-B2 (PLXNB2) is the functional receptor of hRNase5/ANG in several cell types, including endothelial, cancer, neuronal, and normal and malignant stem/progenitor cells." (PMID 30449278, 2018). "Two other PLXNB2 mutations (encoding R531P and L1058S amino acid changes) were found in independent CUP samples, from which it was not possible to derive ex vivo primary cancer cell models." (PMID 36722641, 2023).
infection (2 papers, 2022 to 2023). The state of being infected such as from the introduction of a foreign agent such as serum, vaccine, antigenic substance or organism. "Infection with UT127 led to the expression of the M1 markers IL12RB, IL2RB, and IFNG, concomitantly expressing the M2 markers CTLA4, IL10, and PLXNB2." (PMID 35163725, 2022).
inflammation (1 paper, 2021). Aberrant reaction of the microcirculation characterized by movement of fluid and leukocytes from the blood into extravascular tissues. "Our investigation demonstrated that OAEs (containing PLXNB2) or exogenous PLXNB2 sensitization could augment or propagate OVA challenge–induced airway inflammation." (PMID 34414666, 2021).
psychiatric disorder (1 paper, 2022). A disorder characterized by behavioral and/or psychological abnormalities, often accompanied by physical symptoms. "Nevertheless, our results warrant further research on PLXNB2 and its ligands in psychiatric disorders in the future." (PMID 36325348, 2022).
PLXNB2 also shares sentences with these, for which no sentence is quoted: acute myeloid leukaemia (3 papers); hepatocellular carcinoma (3); neuroblastoma (2); age (1); amelogenesis imperfecta (1); asthenozoospermia (1); astrocytoma (1); autism spectrum disorder (1); cervical cancer (1); clear cell renal cell carcinoma (1); colon tumours (1); colorectal carcinoma (1); COVID-19 (1); cutaneous squamous cell carcinoma (1); esophageal squamous cell carcinoma (1); genetic disease (1); hematopoietic cancers (1); Hyperkeratosis (1); Hypertension (1); kidney disorder (1); lung carcinoma (1); lymphoedema (1); metastatic prostate carcinoma (1); multiple sclerosis (1); myxoma (1); Neuroendocrine tumor (1); neuropathy (1); non-small cell lung carcinoma (1); oral cancer (1); osteosarcoma (1).
A further 3 diseases each share a sentence with PLXNB2 in 1 paper.